BRCA1 (BRCA1 DNA repair associated)
Diseases named in the same sentence as BRCA1 in open-access papers (continued):
Sharing a sentence is not in itself a finding about the gene and the disease.
breast cancer (continued). "Investigating how high risk genetic mutations effect the age of onset we find that in patients <40 years old 5.3% of breast cancer cases are due to mutations in the BReast CAncer susceptibility gene 1 (BRCA1)." (PMID 26010605, 2015). "In follow-up studies, annual MRI significantly reduced the incidence of advanced-stage breast cancers in BRCA1/2 mutation carriers and detected the majority of breast cancers at an early and favorable stage." (PMID 26000714, 2015). "In previous study, most sporadic and BRCA1-associated, basal-like breast cancer showed two active X chromosomes and loss of XCI (61%), reactivation of XCI (22%), and gain of Xa (16%)." (PMID 25742136, 2015). "After having developed unilateral breast cancer, BRCA1/2 mutation carriers are also at increased risk of subsequent contralateral breast cancer." (PMID 26000714, 2015). "For example, a shift in BRCA1 cellular localization often occurs in human breast cancers of differentiated grade and patients with BRCA1 mutations." (PMID 25908947, 2015). "Together, these results corroborate the association between variation at the HMMR locus and breast cancer risk in BRCA1 mutation carriers." (PMID 25830658, 2015). "Best-evidence synthesis: a summary of the available evidence for the relation between BRCA1 mutation carriership and breast cancer prognosis." (PMID 25816289, 2015). "Over the last decade the discovery of genetic testing for breast cancer susceptibility genes (such as BRCA1 & BRCA2) has seen a rise in preemptive screening in many countries, particularly where a strong family history of breast cancer has been observed." (PMID 26010605, 2015). "Because BRCA1-associated breast cancer has an early onset, prophylactic mastectomy must be undertaken at younger age to provide a maximum protective effect." (PMID 26052370, 2015). "Most sporadic breast and ovarian cancers express low levels of the breast cancer susceptibility gene, BRCA1." (PMID 25762631, 2015). "The hypermethylation of BRCA1/2 in promoter regions results in the inactivation of function and increases the risk of breast cancer." (PMID 25774687, 2015). "In the TNBC group, mutations in BRCA1 increased from 18.4% in patients unselected for age to 33.3% in patients with early onset breast cancer." (PMID 26083025, 2015). "Mutations confer a high risk of breast and ovarian cancer with estimated breast cancer penetrances of 60% for BRCA1 and 55% for BRCA2 by age 70 years." (PMID 25848941, 2015). "Due to the substantial risk of breast cancer conferred by the BRCA1 and BRCA2 mutations, development of prevention strategies for mutation carriers is imperative." (PMID 26496879, 2015). "A number of normal single nucleotide polymorphisms (SNPs) associated with breast cancer in the general population have been demonstrated to modify the penetrance of BRCA1." (PMID 26052370, 2015). "EFA was studied in a preclinical murine model for breast cancer based on BRCA1 (BReast CAncer 1) deficiency." (PMID 25866814, 2015). "Increased risk of breast cancer associated with rs3803662 was confirmed in BRCA1/BRCA2 mutation carriers." (PMID 26239137, 2015). "Researchers have established that these genes can also be involved in the development of non-hereditary, sporadic tumours, as a proportion of ovarian and breast cancers contain somatic (tumour only) BRCA1 and BRCA2 pathogenic variants." (PMID 25859162, 2015). "Nonetheless, BRCA1/2 mutations are rare in the general population and cause approximately 2 % of all breast cancers diagnosed." (PMID 26236408, 2015). "Finding is consistent with other studies; the BRCA1 gene mutation carriers at the time of the diagnosis were younger than sporadic breast cancer patients." (PMID 25705321, 2015). "BRCA1 mutation accounts for nearly half of familial breast cancers, but BRCA1 is also down-regulated in sporadic breast tumors without germline mutation." (PMID 25650659, 2015).
breast cancer (continued). "Germ-line mutations in the BRCA1 or BRCA2 genes are the most common causes of breast cancer predisposition resulting in a 70% and 60% lifetime risk of developing breast cancer, respectively." (PMID 26378051, 2015). "The other is the Breast Cancer 1 (BRCA1) susceptibility protein which is responsible for DNA repair and mutations of which have been correlated with the occurrence of breast cancer." (PMID 26150827, 2015). "Our results have highlighted the contribution of BRCA1/2 germline mutations in South African breast cancer patients with triple negative breast tumours and/or premenopausal breast cancer of different ethnicities." (PMID 26577449, 2015). "Conflicting conclusions have been published regarding breast cancer survival of BRCA1/2 mutation carriers." (PMID 25816289, 2015). "As a consequence, BRCA1 associated breast cancers require a specially tailored therapeutic regimen, since the frequent lack of hormone receptors (ER/PR) or Her2 extensively narrows the application of (anti-)endocrine therapies." (PMID 26029931, 2015). "Though the focus of our review was to determine the association between breast cancer prognosis and carriership of the BRCA1 and BRCA2 mutations separately, there were many studies combining both groups in their analyses." (PMID 25816289, 2015). "The estimated HRs indicating the risk for breast cancer at specific regions of the BRCA1/2 mutation was regressed on the log of free serum OPG (pg/ml), adjusted for age at sample at cycle day." (PMID 26629528, 2015). "In early-onset breast cancers, associated with mutations on BRCA1, CD133+ cells show CSCs properties." (PMID 26504780, 2015). "Individuals carrying a germ-line mutation of the BRCA1 gene are at high risk of developing the hereditary form of breast (and ovarian) cancers, which represents approximately 3% of all breast cancer patients." (PMID 25762631, 2015). "Patients carrying a BRCA1 mutation (n = 38) were diagnosed with high grade (G3, p = 0.025), pT1 (p = 0.008) and pN0 (p = 0.040) staged breast cancer significantly more often than sporadic cancer cases (n = 86)." (PMID 26029931, 2015). "Loss of XCI is frequent in basal-like subtype and BRCA1 mutation-associated breast cancers, which show aggressive behavior." (PMID 25742136, 2015). "This suggested a possibility that aberrant methylation of BRCA1 promoter was correlated with an increased risk of breast cancer." (PMID 26643130, 2015). "To evaluate the putative association between PIG3 and BRCA1 with overall survival (OS) in human breast cancer, we performed immunohistochemical (IHC) staining of these proteins in malignant tumor samples from 149 patients using a tissue microarray." (PMID 25797244, 2015). "Females who carry mutations in the BRCA1 gene have an 80% chance of developing breast cancer during their lifetime, and a 65% chance of developing a second breast cancer prior to the age of 70 years." (PMID 25624909, 2015). "BRCA1 is the susceptibility gene of breast cancer and regulates cell apoptosis and repairs DNA damage." (PMID 25646628, 2015). "Crude odds ratio with 95% confidence interval were used to assess the association of BRCA1 promoter methylation and the risk or clinicopathologic characteristics of breast cancers under fixed or random effect model." (PMID 26643130, 2015). "Retrospective analyses have indicated that bilateral risk reduction mastectomy (BRRM) decreases breast cancer risk by at least 90 % in BRCA1 and BRCA2 mutation carries." (PMID 26669313, 2015). "A recent case–control study in BRCA1 carriers found that oral contraceptives use before age 25 increases the risk of early onset breast cancer among BRCA1 mutation carriers and the risk increases with duration of use." (PMID 26669313, 2015).
breast cancer (continued). "Analyses included 5,752 patients from BCAC cohorts, including cases not known to be BRCA1/2 carriers, and 107 breast cancer patients from one study of familial breast cancer patients with BRCA1/2 mutations." (PMID 26137966, 2015). "In order to establish an accurate prognosis in breast cancer patients through the identification of BRCA1 sequence variants, a number of specific screening procedures, which are both cost- and time- effective have been developed." (PMID 25885115, 2015). "There has been observed a weak correlation between BRCA1 mutation status and medullar histology of breast cancer." (PMID 25705321, 2015). "Only 10% to 24% of BRCA1-associated breast cancers are estrogen receptor–positive, whereas 65% to 79% of BRCA2-associated breast cancers are positive for this receptor." (PMID 26557407, 2015). "Major advances in the understanding of breast cancer susceptibility were made in the 1990s when the two major high-risk breast cancer and ovarian cancer predisposition genes BRCA1 and BRCA2 were identified." (PMID 26082817, 2015). "We used the reported hazard ratios (HR) for breast cancer based on the nucleotide position of the BRCA1 and BRCA2 mutation." (PMID 26629528, 2015). "Estimated ORs for the association of FokI and BsmI SNPs with breast cancer by BRCA1/2 status (complete and reduced covariate model)." (PMID 26517870, 2015). "Although somatic BRCA1 mutations are rare in sporadic breast cancer, BRCA1 expression is down regulated in ~30% of sporadic cases." (PMID 26379698, 2015). "In this study, we investigated to what extent mtDNA variability modified breast cancer risk in individuals carrying pathogenic mutations in BRCA1/2." (PMID 25925750, 2015). "BRCA1 has been shown to directly affect the IGF-1R pathway and studies have suggested that BRCA1/2 deficient breast cancer cells are associated with elevated expression of Insulin like growth factor-1 receptor (IGF-1R)." (PMID 26510816, 2015). "To study docetaxel resistance, we used a genetically engineered mouse model for BRCA1-mutated breast cancer." (PMID 25890200, 2015). "The first objective of this study was to investigate the association between AhR expression and/or activation and Brca-1 promoter methylation status in mammary tumors." (PMID 26715507, 2015). "Hereditary mutations in BRCA1 result in a predisposition to breast cancer, and BRCA1 expression is down-regulated in ~30% of sporadic cases." (PMID 26379698, 2015). "PARP inhibitors and their effect on triple negative and BRCA1/2 mutation related breast cancers are the subject of much interest." (PMID 25692038, 2015). "(2006) observed a 50% reduction in contralateral breast cancer in carriers of both BRCA1 and BRCA2 mutations when tamoxifen was given as treatment for the initial breast cancer diagnosis." (PMID 26557407, 2015). "Given that BRCA1-associated breast cancers often belong to the TNBC subtype, and both frequently show morphologic evidence of hypoxia (central fibrosis and necrosis), an augmented expression of HIF-1α in tumors with a triple-negative phenotype was anticipated." (PMID 26046764, 2015). "With regards to genetics, PALB2 (Partner And Localizer of BRCA2) was presented as a new high-risk breast cancer gene identified and the reasons why it should be added to genetic testing for BRCA1/BRCA2 were clearly explained." (PMID 25729421, 2015). "Women carrying a germline BRCA1 mutation have a 57–65% chance of developing breast cancer before the age of 70 years, which for BRCA2 mutation carriers is 45–55%." (PMID 26000714, 2015). "Among the disease-associated genomic regions, TOX3 and FGFR2 genes have been identified as breast cancer susceptibility genes in BRCA1/2-wild-type breast cancer patients from Sardinia." (PMID 25956309, 2015).
breast cancer (continued). "Risk reduction of breast cancer after RRSO was estimated to be 53–72 % in BRCA1/2 mutation carriers in several studies." (PMID 26264902, 2015). "It represents the first biological demonstration for the existence of a sporadic HER2-positive breast cancer independent from BRCA loss of function in a woman carrier of a deleterious BRCA1 mutation." (PMID 26426992, 2015). "Study group was made of 18 triple-negative breast cancer patients harboring the BRCA1 gene mutations and 32 triple-negative sporadic breast cancer patients." (PMID 25705321, 2015). "A germline polymorphism near PTHLH was associated with increased risk for the development of both sporadic and BRCA1-mutation-associated breast cancer, and tumour expression of PTHLH promotes the formation of osteolytic lesions in bone." (PMID 25633981, 2015). "For example, there are considerable similarities between basal-like and BRCA1-mutated breast cancers, and these cancers arise from transformation of a basal cell in normal breast epithelium through BRCA1 dysfunction." (PMID 26400441, 2015). "As previously observed, triple-negative breast cancers tend to harbor BRCA1/2 mutation which appears to be slightly overrepresented in PALB2-related breast cancers." (PMID 26489409, 2015). "BRCA1/2 germline mutation carriers are at an increased risk of developing ovarian and breast cancer." (PMID 26510816, 2015). "ANXA8 is strongly expressed in BRCA1-associated breast cancers and these cancers have recently been shown to originate from ERα−ve luminal progenitor cells." (PMID 25803307, 2015). "Mammographic density is a strong and independent risk factor for breast cancer, reported to exceed all other risk factors apart from age and the presence of mutations in high penetrance breast cancer predisposition genes such as BRCA1 and BRCA2." (PMID 26110820, 2015). "For instance, the breast cancer susceptibility gene BRCA1 was shown to be involved in all phases of the cell cycle and modulate orderly events during cell cycle progression." (PMID 25800793, 2015). "The existence of a family history of breast cancer is one of the strongest risk factors, and the known pathogenic mutations in the BRCA1 and BRCA2 genes confer a life-time risk of breast cancer of 60–85% and 55–85%, respectively." (PMID 25339628, 2015). "Many cases of hereditary breast cancer are due to mutations in either the BRCA1 gene or the BRCA2 gene." (PMID 25910040, 2015). "Relative tissue concentrations of choline compounds are higher in docetaxel resistant than in sensitive BRCA1-mutated mouse mammary tumors, but in the first days after docetaxel treatment only in the sensitive tumors an increase of these compounds is observed." (PMID 25890200, 2015). "Our overall mutation detection rate of BRCA1/2 mutations in the black premenopausal breast cancer patients was 6.5 % (5/77)." (PMID 26577449, 2015). "Loss of X chromosome inactivation (XCI) is observed in breast and ovarian cancers, and is frequent in basal-like subtype and BRCA1 mutation-associated breast cancers." (PMID 25742136, 2015). "This type of association was also found in breast cancer where experimental and in vitro works demonstrate that BRCA1 is a mammary stem and progenitor cells regulator, allowing their differentiation into mature luminal and myoepithelial cells." (PMID 26504831, 2015). "Using the best-evidence synthesis, we concluded there is indecisive evidence for an association between BRCA1 mutation carriership and unadjusted/adjusted breast cancer-specific survival." (PMID 25816289, 2015). "The association of HMMR rs299290 with breast cancer risk in BRCA1 mutation carriers was confirmed: per-allele hazard ratio (HR) = 1.10, 95% confidence interval (CI) 1.04 – 1.15, p = 1.9 x 10−4 (false discovery rate (FDR)-adjusted p = 0.043)." (PMID 25830658, 2015).
breast cancer (continued). "With respect to the high propensity of BRCA mutations in familial breast cancer, the facilitative role of BRCA1 in DNA damage response and repair is thought to be facilitated by other breast cancer-associated ubiquitin E3 ligases." (PMID 28536406, 2015). "It is already known that breast cancers in carriers of BRCA1 mutations exhibit different pathological characteristics compared to tumours in non-carriers, leading to treatment differences." (PMID 25816289, 2015). "Breast cancer susceptibility gene 1 (BRCA1) located at chromosome 17q12-21 is a classic tumor suppressor gene, and has been considered as a significant role in hereditary breast cancers." (PMID 26643130, 2015). "The majority of the studies conducted in different countries differ in their results for the pathological features of patients with breast cancer associated with the type of BRCA1 gene mutation." (PMID 25624909, 2015). "Previous research by our group and by others has shown that a proportion of TNBC shares similarities with BRCA1-mutated breast cancers." (PMID 26433948, 2015). "In this context, recent clinical data have shown that BRCA1-associated breast cancers appeared to be more sensitive to platinum agents in neoadjuvant chemotherapy than non-hereditary tumors." (PMID 26490435, 2015). "Women who carry a germline mutation in BRCA1 have a lifetime risk of 50%–85% of developing breast cancer and 12%–60% of developing ovarian cancer." (PMID 26061043, 2015). "Loss of BRCA1, a familial breast cancer susceptible gene, through mutation or epigenetic dysregulation often leads to tumors with a basal-like phenotype." (PMID 25679396, 2015). "We describe the case of a woman carrying a germline pathogenic BRCA1 mutation diagnosed with a breast cancer overexpressing HER2." (PMID 26426992, 2015). "Second, we investigated trends over time; something that was not done in some earlier, large studies of risk reducing surgery in BRCA1/2 mutation carriers with breast cancer." (PMID 25700605, 2015). "When we looked specifically at BRCA1/2 mutation carriers, breast cancer patients had a lower BMI compared to controls, with 92 % of cases versus 85 % of controls having BMI <30 (P value = 0.03)." (PMID 26163143, 2015). "The results of this study expand on the previous suggestion that variation in HMMR is specifically associated with breast cancer risk in BRCA1 mutation carriers." (PMID 25830658, 2015). "We found a significantly higher expression of ANXA1 in tumors from familial breast cancer patients with BRCA1/2 mutations compared with hospital and population-based breast cancer series." (PMID 26137966, 2015). "A variation in breast cancer risk associated with parity has been evidenced according to the type of mutation in the DNA repair gene BRCA1, acting in the same pathway as ATM." (PMID 25879635, 2015). "Approximately 30% of all hereditary breast cancer patients and the majority of breast and ovarian cancer patients harbor germline mutations in the BRCA1/2 genes." (PMID 26083025, 2015). "Majority of the known breast cancer susceptibility genes have a role in DNA repair and the most important high-risk genes BRCA1 and BRCA2 are specifically involved in the homologous recombination repair (HRR) of DNA double-strand breaks." (PMID 25918678, 2015). "PARP inhibition is a promising strategy for the treatment of breast cancer associated with germline BRCA1/2 mutations and papillary serous ovarian cancers." (PMID 26268938, 2015). "Of interest, germline mutations in BRCA1 versus BRCA2 associate with different subtypes of breast cancer." (PMID 25869442, 2015). "Recent evidence indicates that BRCA1/2 mutation triggered breast cancer risk also depends on the actual site of the germline mutation." (PMID 26629528, 2015).